HIF1A (hypoxia inducible factor 1 subunit alpha)
Diseases named in the same sentence as HIF1A in open-access papers (continued):
Sharing a sentence is not in itself a finding about the gene and the disease.
breast cancer (continued). "Another example is LINC00649, which increased the stability and thus the levels of HIF-1α mRNA by interacting with the nuclear factor 90 (NF90)/NF45 complex, which is a signaling cascade responsive to double-stranded DNA, inducing proliferation of breast cancer cells." (PMID 35626715, 2022). "Interestingly, increased expression of HIF1α and G3BP1, two YB-1 translational targets and elements of a stress-adaptive programme, mirrored the levels of YB-1 in both transformed primary and established MDA-MB-231 breast cancer cells." (PMID 34294889, 2022). "HIF-1α is a well-appreciated target for cancer therapies, and drugs that indirectly inhibit hypoxia/HIF-1α signalling such as digoxin and acriflavine, have been reported to have relevant impacts – for example decreasing lung metastasis in an orthotopic breast cancer model." (PMID 35392965, 2022). "In addition, induction of HIF-1α protein by IL-1β and IGF-I has been reported in other cell lines, such as human osteoarthritic chondrocytes, cytotrophoblast cells, human gingival and synovial fibroblasts, and colon and breast cancer cells." (PMID 36497143, 2022). "The expression of LDH-A, an enzyme important in the production of lactic acid, and hypoxia-inducible factor-1α (HIF-1α), a major marker of hypoxia, was increased in breast cancer cells compared with normal breast cells; the expression of PD-L1 and pY-STAT3 was also increased in breast cancer cells." (PMID 35927628, 2022). "It is known that HIF-1α is a metabolic regulator that plays an important role in glycolysis metabolism, we further investigated whether JFK functions in hypoxia-induced glycolysis of breast cancer cells." (PMID 34336836, 2021). "Similarly, in breast cancer cells HIF-1α induces immediately VEGF that favors neo-angiogenesis and cell survival, but prolonged hypoxia activates the IREα/XBP-1 axis that induces miR-153, a negative regulator of HIF-1α." (PMID 33423689, 2021). "Therefore, the present study aimed to evaluate the modulatory effect of regorafenib on the P2X7/HIF-1α/VEGF, P2X7/P38, P2X7/ERK/NF-κB, and P2X7/beclin 1 pathways on the MCF7 breast cancer cell line and its impact on different signaling pathways involved in breast cancer progression." (PMID 34940128, 2021). "Chronic hypoxia induces hypomethylation of HIF1A promoter as well as promoters of rate-limiting glycolytic genes PKM and LDHA, which lead to elevated transcript and protein levels and contribute to enhanced glycolytic activity of CAFs derived from breast cancer patients." (PMID 34202979, 2021). "Therefore, evaluation of the expression of HIF-1α and GLUT1 in blood may be a useful laboratory tool to complement the diagnosis of breast cancer, in addition to being useful for follow-up of patients and of women with a family history of breast cancer." (PMID 33888756, 2021). "Of note, not all breast cancer samples expressing HIF-1α are necessarily hypoxic." (PMID 34671319, 2021). "However, the Kaplan–Meier (KM) plot analysis revealed that ZC3H12A is a favorable marker for the prognosis of patients with breast cancer, which may counteract the mechanism of TARBP2-mediated deubiquitination of HIF-1α." (PMID 35008634, 2021). "Furthermore, the involvement of lactate in modulating cellular metabolism is demonstrated by lactate-induced transcriptional activation of HIF1A in A549 cell, and this effect of lactate on HIF1A transcription was also recently observed in human MCF7 breast cancer cell." (PMID 34150616, 2021). "Moreover, expression of HIF-1α and GLUT1 is significantly higher in peripheral blood samples from breast cancer patients than that found in healthy women, a result that points to their expression detection in this biological matrix as a potential diagnostic tool of this disease." (PMID 33888756, 2021).
breast cancer (continued). "Notably, the absence of BNIP3 in mammary cancer causes accumulation of dysfunctional mitochondria and elevated mtROS that upregulates HIF-1α and HIF-1α target genes, including those involved in cancer aggressiveness." (PMID 34067882, 2021). "Concerning the inhibition of the tumorigenesis and metastasis of breast cancer, ISL can rectify the abnormal PI3K/AKT, NF-kB, and p38 signaling pathways in order to reduce the occurrence of metastasis through correcting the expression of MMP-2, MMP-7, MMP-9, VEGF, and HIF-1α." (PMID 33401375, 2021). "Therefore, evaluation of the expression of HIF-1α and GLUT1 in the blood may be a useful laboratory tool to complement the diagnosis of breast cancer." (PMID 33888756, 2021). "To gain further support for the impacts of this HIF-1α-JFK axis on breast cancer, and seeking to add clinicopathologically relevant data to our observations, we collected samples from resected breast carcinomas – paired with adjacent normal mammary tissues – from 14 breast cancer patients." (PMID 34336836, 2021). "According to reports, the HIF-1α/miR-210 signalling axis regulates mitochondrial free radicals in response to hypoxia in cancer cells by targeting downregulation of ISCU expression, which correlates with poor prognosis in breast cancer and HNSCC and good prognosis in renal cancer." (PMID 34488769, 2021). "Moreover, HIF1-α inhibition synergized with DC-based immunotherapy was shown to result in tumor regression and improved survival by augmenting the proliferation and function of cytotoxic T lymphocytes and increasing IFN-γ production in a breast cancer model." (PMID 33422072, 2021). "Indeed, hypoxic lncRNA KB-1980E6.3 was significantly decreased in HIF-1α knockdown breast cancer cells rather than in HIF-2α silenced cells under hypoxia conditions." (PMID 33469161, 2021). "Specifically, knockout of HIF-1α in the MMTV-PyMT mouse model was reported to suppress both primary tumor growth and lung metastasis, which is consistent with our observation that JFK overexpression promotes mammary tumor initiation and metastasis in the MMTV-PyMT mouse model." (PMID 34336836, 2021). "LINK-A promotes HIF1α phosphorylation at tyrosine 565 and tryptophan 797 loci by regulating BRK and LRRK2; this process leads to the activation of HIF1α signals under normoxia conditions in triple-negative breast cancer (TNBC), resulting in glycolysis restructuring and breast cancer tumorigenesis." (PMID 32878637, 2020). "However, in breast cancer cells, both overexpression of HIF-1α and hypoxia-mimetic agent CoCl2 did not affect the BMAL1 protein expression." (PMID 32316196, 2020). "Therefore, to elucidate the intracellular signaling pathway that mediates XCL1-induced breast cancer cell migration, the effects of the XCL1–XCR1 axis on EMT markers, ERK1/2 activation, and HIF-1α expression were also examined in MDA-MB-231 and SK-BR-3 cells in this study." (PMID 33374849, 2020). "As IL-1β may contribute to breast cancer development and metastasis and may regulate the migratory phenotype of TNBC cells through HIF-1α, we sought to evaluate whether IL-1β could be involved in the activation of a hypoxia-related gene signature in TNBC patients." (PMID 32778144, 2020). "For example, in breast cancer, the over-expression of SIRT3 decreases the rate of glycolysis and inhibited cell proliferation followed by tumor suppression, whereas down-regulation of SIRT3 increased ROS production leading to HIF-1α stabilization and upregulation of HIF-1α target genes." (PMID 32252351, 2020). "However, HIF1α protein levels induced by hypoxia were neither affected by CAV1 overexpression in HT29(US) colon cancer cells or by CAV1 knockdown in the breast cancer cell line MDA-MB-231." (PMID 32825247, 2020).
breast cancer (continued). "Previous studies showed that hypoxia-inducible factor-1α (HIF-1α), a master regulator protein in hypoxia, plays an essential role in cancer invasion and metastasis, and evidence suggests that high HIF-1α expression displays poor prognosis for cancer patients, particularly those with breast cancer." (PMID 32858793, 2020). "However, there were no reports concerning the relationship between HIF‐1α, Kindlin‐2, and breast cancer stiffness." (PMID 32436609, 2020). "Lactate-induced TAM polarization and its pro-tumorigenic effects in breast cancer has been attributed to TAM-specific extracellular signal-regulated kinase (ERK)/STAT3 activation, stimulated expression of vascular endothelial growth factor (VEGF) and arginase-1 (ARG1), and stabilization of HIF-1a." (PMID 33324565, 2020). "When hypoxic environment advances, HIF1A is overexpressed and promoting upregulation of various target genes, including carbonic anhydrase IX (CAIX), a transmembrane glycoprotein to prevent intracellular acidosis, allowing breast cancer cells to undergo metabolic adaptation to hypoxia." (PMID 32212787, 2020). "The first question is whether there is a common underlying mechanism at work for methylation at non-CpG sites in the HIF-1α promoter in breast cancer cells." (PMID 30940798, 2019). "However, knowledge is lacking on the non-CpGs methylation of HIF-1α promoter in breast cancer cells." (PMID 30940798, 2019). "To address which methyltransferases are responsible for DNA methylation at CpG sites and non-CpGs within the first exon of the HIF-1α gene, we detected the endogenous expression levels and patterns of DNMT3a and DNMT3b in various breast cancer cell lines by western blot." (PMID 30940798, 2019). "One explanation of the more frequent HIF-1α-positivity in ERα-negative breast cancer could be that these tumors have a high proliferation rate, leading to hypoxic foci." (PMID 31821370, 2019). "In another word, although HIF-1alpha is primary regulated at the post-translational levels, there is transcriptional regulation of HIF-1alpha in breast cancer cells, such as the methylation at CpG and non-CpG dinucleotides in the HIF-1α promoter around the TSS which is mainly mediated by DNMT3a.." (PMID 30940798, 2019). "The HIF-1α inhibitor digoxin, which exerts anti-cancer effects by reducing the protein levels of HIF-1α and its target genes (GLUT1, HK, and VEGF) is currently in phase II clinical trials to treat several cancers, including head and neck cancer, Kaposi’s sarcoma, and breast cancer." (PMID 31817259, 2019). "Collectively, these findings suggest that CpG and non-CpG methylation within the HIF-1α gene promoter and first exon may play key roles in HIF-1α expression in breast cancer, and that this methylation at CpG and non-CpG sites is regulated by DNMT3a." (PMID 30940798, 2019). "Overall, these data suggest that DNA methylation at CpG and non-CpG sites may play vital roles in HIF-1α expression during breast cancer progression." (PMID 30940798, 2019). "Previous studies have revealed that expression of USP28 was strongly elevated in human colon and breast carcinomas, and overexpression of USP28 enhanced HIF-1α-dependent angiogenesis and promoted colorectal cancer, suggesting that it might play a critical role in tumor cellular pathways." (PMID 30622440, 2019).
breast cancer (continued). "In this regard, more insights into the signaling network between Notch, HIF-1α, and GPER in breast cancer EMT could provide new hints for the generation of novel combination strategies targeting breast cancer progression and overcoming anti-cancer drug resistance." (PMID 29996493, 2018). "It has been shown through gene expression profiling of hypoxic mammary tumours that known targets of the HER2/neu pathway are elevated, which suggests that hypoxic condition and HER2 overexpression share phenotypic and genetic components through HIF-1α regulation." (PMID 29865880, 2018). "Consistent with ChIP and luciferase reporter data, CSRP2 and HIF-1α protein levels were significantly correlated in both pre-clinical and patient tumour specimens, supporting that tumour hypoxia is an important determinant of CSRP2 up-regulation in breast cancer." (PMID 29976963, 2018). "In addition, breast cancer tissue microarrays have shown that in breast cancer samples, WWOX expression is inversely correlated with levels of the glucose transporter GLUT1, which is known to be a direct target of HIF1α." (PMID 30211123, 2018). "Since WWOX function is usually lost in breast cancer, it will be interesting to test whether a small molecule that resembles WWOX WW domain would inhibit the function of HIF1α and shifts cancer cell metabolism from a glycolysis dependent to a normal metabolism." (PMID 30619734, 2018). "In addition to HIF-1α, systematic ChIP-seq data of human hypoxic breast cancer cells revealed that, HIF-2α also bound with lncRNA promoters and even in a higher proportion than HIF-1α, suggesting a pivotal role of HIF-2α in the regulation of the long noncoding transcriptome upon hypoxia." (PMID 28789687, 2017). "Studies in breast cancer cells have observed no change in Akt total protein or phosphorylation following TD, suggesting this may not effect HIF-1α stabilization." (PMID 29045486, 2017). "However, there is a lack of reports on HIF-1α expression in African breast cancer, which has a poor prognosis, and novel treatment targets must therefore be established." (PMID 26760782, 2016). "While HIF-1α has not reached an independent prognostic marker status in our study and in most of previous trials, it is doubtable that it will be of an imminent value for diagnostics in breast cancer." (PMID 27780920, 2016). "Whereas studies in breast cancer cells have indicated that HIF-1α crucially regulates expression of stem cell factor (SCF), a c-KIT ligand, results on small-cell lung cancer cells indicated that activated SCF-c-KIT stimulated HIF-1α-mediated VEGF expression via PI3K/Akt activation." (PMID 26760782, 2016). "Given that some of key signaling pathways, such as HIF1α, PI3K/AKT and MAPK/ERK1/2 pathways make a substantial contribution to govern proliferative, migrating and invasive phenotypes in breast cancer cells, we considered whether there was any correlation between SEPT2/7 functions and these pathways." (PMID 27557506, 2016). "ER+ PgR+ Ki-67- breast cancer cells were successfully recognized as nuclei with a purple color, indicating that light-field chromogenic triple immunostaining using these chromogens is suitable for use in searching for SOX2+ (or NANOG+) HIF-1α+ RNApII-S2P-/low cells in astrocytoma tissues." (PMID 26799577, 2016). "Moreover, the SCF/c-kit binding has been reported to increase hypoxia-inducible factor-1α (HIF-1α) protein synthesis by the PI3K and Ras/MEK/ERK pathways in pancreatic cancer cells under normoxia, and hypoxia up-regulated SCF gene expression in breast cancer cells through HIF-1α." (PMID 25799412, 2015). "Furthermore, BRCA1/2-related breast cancers also presented a higher percentage of VEGFA, HIF1A, FAK and ANGPT2 gene overexpression compared to the BRCAX breast tumour group (VEGFA: 62% vs 9%, p=0.04; HIF1A: 62% vs 0%, p=0.004; FAK: 62% vs 18%, p=0.073; ANGPT2: 50% vs 45%, p= 1.00)." (PMID 25333258, 2015).
breast cancer (continued). "However, it is felt that CAP-independent translation cannot fully account for the translational capacity of hypoxic cells, as recent studies show that HIF1α and HIF2α can drive the CAP-dependent translation of a subset of mRNAs required for breast cancer cell growth." (PMID 26501324, 2015). "Interestingly, we found that HIF-1α stabilization promotes membrane P-cadherin expression in breast cancer cells, although no alterations were detected in CDH3 mRNA levels after CoCl2 treatment." (PMID 25269858, 2014). "Finally, we showed that P-cadherin silencing significantly decreases the mammosphere forming efficiency in the same range as the silencing of HIF-1α, CAIX or GLUT1, validating that all these markers are being expressed by the same breast cancer stem cell population." (PMID 25269858, 2014). "Interestingly, several studies have shown that the presence of HIF-1α is a negative prognostic factor for human breast cancer." (PMID 25128202, 2014). "Furthermore, we previously identified that HIF-1α could directly inhibit VASP transcription during the TNF-α-induced metastasis and adhesion of breast cancer MCF-7 cells." (PMID 25051011, 2014). "The effect of Celastrol in enhancing HIF-1α expression was not cell-type specific because we also detected the same changes in human mammary carcinoma MCF-7 cells, cervical cancer HeLa cells, prostate cancer PC-3 cells and non-small cell lung cancer H1299 cells." (PMID 25383959, 2014). "However, the regulation of aromatase expression by HIF-1α in breast cancer has not been characterized." (PMID 23566437, 2013). "In order to see whether the decreased HIF-1α protein level was caused by accelerated proteasome degradation by ISL, we firstly added cycloheximide, a protein synthesis inhibitor, to treat breast cancer cells with or without ISL." (PMID 23861918, 2013). "For example, estrogen could induce the expression of VEGF and activation of HIF-1α in uterus mainly expressing estrogen receptor α, but estrogen inhibited angiogenesis and reduced the expression of VEGF in breast cancer which mainly expressed estrogen receptor beta." (PMID 24348555, 2013). "With this in mind we used cell culture techniques and rodent models to examine, both in vitro and in vivo, the capacity of YC-1 as a HIF-1α inhibitor which might be used to control progestin-stimulated PR-dependent VEGF secretion and progression of progestin-dependent breast cancer." (PMID 23123638, 2013). "In vivo study also demonstrated that epigallocatechin could significantly inhibit breast cancer growth, HIF-1α/LDH-A expression and trigger apoptosis without bringing toxic effects." (PMID 23457597, 2013). "An enhanced activity of HIF-1α under hypoxia has also been observed to result in the up-regulated expression of TGF-β superfamily member, Nodal through the activated Notch pathway in breast cancer cells that in turn contributed to their invasion and metastatic spread." (PMID 23301832, 2013). "Although the role of hypoxia and the HIF-1α transcriptional response in promoting tumor progression and metastasis is well-established, the direct contribution of the HIF family to the regulation of TICs in breast cancer is unknown." (PMID 22225988, 2012). "Thus, the pro-angiogenic effect of E2 on breast cancer cells is not solely dependent on the nuclear translocation of estrogen receptor (ER) but rather on HIF-1α translocation as well." (PMID 23088607, 2012). "Moreover, siRNA against c-Src, Akt and mTOR was observed to inhibit the phosphorylation of 4E-BP1 and p70S6K as well as exhibited blunted HIF-1α expression in response to E2, suggesting the importance of mTOR signalling in the elevated HIF-1α levels in breast cancer cells." (PMID 21897387, 2011). "However, our results showed that decreased activation of PI3K or ERK by inhibitor did not change the activated HIF-1α mRNA transcription level under hypoxia in MCF-7 human breast cancer cells." (PMID 21980400, 2011).